SEC23IP (SEC23 interacting protein)
Description:
Plays a role in the organization of endoplasmic reticulum exit sites. Specifically binds to phosphatidylinositol 3-phosphate (PI(3)P), phosphatidylinositol 4-phosphate (PI(4)P) and phosphatidylinositol 5-phosphate (PI(5)P).
Synonyms: MSTP053; p125; iPLA1beta; iPLA1β; p125A; iPLA1A
Tractability: Antibody: UniProt places it where antibodies can reach, with medium confidence. PROTAC: ubiquitination databases record sites on it; its protein half-life has been measured.
Gene: Protein-coding gene on chromosome 10 (119,892,686 to 119,944,657, forward strand). Ensembl gene ENSG00000107651.
Subcellular location: Cytoplasmic vesicle, COPII-coated vesicle membrane; Endoplasmic reticulum
Subcellular location (Human Protein Atlas): Vesicles
Pathways (Reactome):
Vesicle-mediated transport: COPII-mediated vesicle transport
Gene Ontology:
Molecular function: protein binding; RNA binding; phospholipase activity; metal ion binding
Biological process: Golgi organization; intracellular protein transport; spermatid development; endomembrane system organization; endoplasmic reticulum to Golgi vesicle-mediated transport
Cellular component: COPII-coated ER to Golgi transport vesicle; cytoplasm; cytosol; endoplasmic reticulum-Golgi intermediate compartment; Golgi apparatus; endoplasmic reticulum; ER to Golgi transport vesicle membrane
Genetic constraint (gnomAD): Loss-of-function variants: 55 observed, 79.58 expected, observed/expected ratio (o/e) 0.69, 90% interval 0.56 to 0.87. The upper end of that interval is the gene's LOEUF score, 0.87, which puts it in group 3 of 6, group 1 being the genes least tolerant of losing a copy. Missense variants: 890 observed, 953.54 expected, observed/expected ratio (o/e) 0.93, 90% interval 0.88 to 0.99. Synonymous variants: 323 observed, 345.71 expected, observed/expected ratio (o/e) 0.93, 90% interval 0.85 to 1.02.
Homologues: Orthologues: chimpanzee SEC23IP (99% identical), macaque SEC23IP (98% identical), dog SEC23IP (91% identical), pig SEC23IP (91% identical), rabbit SEC23IP (90% identical), rat Sec23ip (88% identical), guinea pig SEC23IP (87% identical), mouse Sec23ip (86% identical), tropical clawed frog sec23ip (66% identical), zebrafish sec23ip (62% identical), Drosophila melanogaster PAPLA1 (25% identical). Paralogues in human: DDHD2 (39% identical), DDHD1 (20% identical).
Diseases named in the same sentence as SEC23IP in open-access papers:
SEC23IP is named in the same sentence as 8 diseases in open-access papers, as found by Europe PMC text mining. Sharing a sentence is not in itself a finding about the gene and the disease. The quoted sentences say what the papers report.
Spastic paraplegia (1 paper, 2023). Complete loss of the ability to move the lower limbs accompanied by spasticity of the lower limbs. "SEC23IP, also known as p12537, is associated with spastic paraplegia 28 and nodular malignant melanoma." (PMID 37865667, 2023).
superficial spreading melanoma (1 paper, 2016). A type of melanoma that typically occurs in light-skinned individuals ranging in age from young adults to the elderly. "Superficial spreading melanoma (SSM) and nodular melanoma (NM characteristically express the eight genes GALNT7, DIS3, FGFR1OP, G3BP2, MTAP, SEC23IP, USO1, and ZNF668." (PMID 27322213, 2016).
SEC23IP also shares sentences with these, for which no sentence is quoted: hereditary spastic paraplegia (1 paper); infection (1); melanoma (1); neurodegenerative disease (1); paraplegia (1); tumour (1).